LINC02303 (long independently transcribed non-coding RNA 2303)
Synonyms: TRMP
Gene: Long non-coding RNA gene on chromosome 14 (45,706,250 to 45,715,952, reverse strand). Ensembl gene ENSG00000258616.
Diseases named in the same sentence as LINC02303 in open-access papers:
LINC02303 is named in the same sentence as 2 diseases in open-access papers, as found by Europe PMC text mining. Sharing a sentence is not in itself a finding about the gene and the disease.
LINC02303 shares sentences with these, for which no sentence is quoted: cancer (1 paper); tumor (1).